RNU6-1174P (RNA, U6 small nuclear 1174, pseudogene)
Gene: Small nuclear RNA gene on chromosome 3 (134,780,527 to 134,780,627, reverse strand). Ensembl gene ENSG00000253087.
Homologues: Orthologues: chimpanzee U6 (98% identical), macaque U6 (96% identical), mouse Gm22221 (70% identical), rat LOC120094985 (67% identical), guinea pig U6 (60% identical). Paralogues in human: RNU6-1152P (88% identical), RNU6-41P (87% identical), RNU6-1060P (86% identical), RNU6-116P (86% identical), RNU6-211P (86% identical), RNU6-35P (86% identical), RNU6-12P (85% identical), RNU6-13P (85% identical), RNU6-16P (85% identical), RNU6-196P (85% identical), RNU6-25P (85% identical), RNU6-310P (85% identical), and 1290 more.